MTOR (mechanistic target of rapamycin kinase)
Diseases named in the same sentence as MTOR in open-access papers (continued):
Sharing a sentence is not in itself a finding about the gene and the disease.
bladder cancer (continued). "The mTOR signaling inhibition upregulates autophagy-mediated GPX4 degradation, thereby promoting ferroptosis of bladder cancer cells." (PMID 36923942, 2023). "We demonstrated that in comparison with bladder cancer urothelial cells, hAM homogenate slightly increased the protein levels of PI3K p110α, mTOR and the amount of phosphorylated Akt and mTOR expression." (PMID 37932474, 2023). "The molecular pathway for bladder cancer strongly appears to also involve expression of KDM2B, as well as the mTOR pathway." (PMID 36662841, 2023). "It was shown that ADAMTS9-AS1 promoted the proliferation and migration of bladder cancer cells and inhibited autophagy and apoptosis through the PI3K/AKT/mTOR pathway." (PMID 37872487, 2023). "In bladder cancer, upregulation of ADAMTS9-AS1 was found to be accompanied by activation of the PI3K/AKT/mTOR signaling pathway, whereas downregulation of ADAMTS9-AS1 led to the opposite effect." (PMID 37872487, 2023). "CDCA5 promotes the progression of bladder cancer by dysregulating mitochondria-mediated apoptosis, cell cycle regulation, and activation of the PI3k/AKT/mTOR pathway." (PMID 35354488, 2022). "For example, in bladder cancer, lncRNA TINCR promotes tumor proliferation and invasion by regulating miR-7 and mTOR." (PMID 36157234, 2022). "Then, SC79 (activator of AKT) was used to treat bladder cancer cells transfected with UCHL5 shRNA, and Western blotting analysis showed rescue of p-AKT/p-mTOR protein expression affected by UCHL5 knockdown." (PMID 36428630, 2022). "Although there have been few studies about metformin in bladder cancer, analysis of reviews and published studies revealed that more than 40% of patients with urothelial carcinoma had a dysregulated PI3K/AKT/mTOR pathway." (PMID 35610639, 2022). "Although the risk factors of its occurrence remain to be elucidated, recent development in sequencing technology has identified several genes and pathways which are key drivers of bladder cancer, including cell cycle-related genes, RAS, and PI-3-kinase/mTOR." (PMID 36085200, 2022). "In bladder cancer, PI3K/AKT/mTOR signaling was observed to be constitutively activated in more than 40% of cases." (PMID 35402614, 2022). "All things considered, our findings show that increased UCHL5 expression stimulates AKT/mTOR signaling, subsequently triggering the expression of c-Myc, SLC25A19, and ICAM5, which in turn promotes carcinogenesis in bladder cancer." (PMID 36428630, 2022). "Next, we investigated the relationship between p-mTOR and OTUD5 in bladder cancer tissues using immunohistochemistry." (PMID 36085200, 2022). "Evidence is provided here that OMWW inhibits proliferation of cisplatin and gemcitabine resistant cells in a panel of bladder cancer cell lines by acting on the Cyclin-CDK-axis and the Akt-mTOR signaling cascade." (PMID 35057550, 2022). "In addition, analysis of the Kyoto Encyclopedia of Genes and Genomes pathway revealed that the phosphatidylinositol-3-kinase (PI3K)/AKT/mammalian target of rapamycin (mTOR) signaling pathway may play a crucial role in the mechanism of action of gypenosides against bladder cancer." (PMID 35402614, 2022). "Abnormal expression of mTOR has been described in several types of cancers, including kidney renal clear cell carcinoma (KIRC), bladder cancer (BLCA), primary liver cancer, esophageal carcinoma, and colorectal adenocarcinoma." (PMID 35082928, 2022). "In bladder cancer, somatic alterations that lead to the activation of the PI3K/AKT/mTOR pathway occur in over one-third of cases." (PMID 35852858, 2022). "In bladder cancer cells, the hypoxia-induced HIF-1α activation and VEGF secretion were abolished by magnolol through suppressing VEGFR2/PI3K/Akt/mTOR/p70S6K/4E-BP1 cascade." (PMID 36234977, 2022). "In bladder cancer, depletion of RB transcriptional corepressor 1 activates the E2F3, Myc, and mTOR signaling pathways to facilitate proliferation and restrain apoptosis of cancer cells." (PMID 34644734, 2021).
bladder cancer (continued). "Upregulated RNAs were mainly enriched in pathways in cancer, such as bladder cancer, RIG-I-like receptor signaling pathway, TGF-beta signaling pathway, MAPK signaling pathway, FoxO signaling pathway, and mTOR signaling pathway." (PMID 33987102, 2021). "In three bladder cancer cell lines (RT112, UMUC3 and TCCSUP), SFN treatment significantly suppressed the amount of phosphorylated Akt and phosphorylation of the mTOR subunit Rictor." (PMID 34073079, 2021). "Many signaling pathways are involved in the the survival of bladder cancer cells, including NF-kB, MAPK, mTOR and JAK-STAT." (PMID 34315490, 2021). "Compound 1 was also found to be involved with Akt, mTOR, and MEK-ERK pathways in renal carcinoma cells or the inactivation of EGFR-related pathways in bladder cancer cells." (PMID 34641476, 2021). "In summary, SMYD3 plays critical roles in bladder cancer oncogenesis, such as interactions with IGF-1R and AKT/mTOR in a possible feedback pathway, cell cycle and apoptotic regulation, and autophagy activation via BCLAF1 regulation." (PMID 33637115, 2021). "The dual inhibitor of PI3K and mTOR, GSK2126458, was used in phase I trial of multiple tumor types (sarcoma, kidney, breast, endometrial, oropharyngeal, and bladder cancer)." (PMID 33690666, 2021). "In conclusion, we demonstrated that recombinant human arginase (BCT-100) display good anticancer effects against bladder cancer via apoptosis and autophagy regulated by the ROS-activated AKT/mTOR signaling pathway." (PMID 33791071, 2021). "We selected the possible effective combination of inhibitors using a 3D HTS platform and blocked the downstream (mTOR inhibitor) and upstream (AKT inhibitor) mediators of the PI3K/AKT/mTOR pathway in bladder cancer cells." (PMID 32325639, 2020). "Similar results were obtained through combining the PI3K/mTOR dual inhibitor NVP-BEZ235 with cisplatin in osteosarcoma, triple negative breast cancer and bladder cancer." (PMID 33585182, 2020). "To explore the mechanism by which O-GlcNAcylation regulates the basal autophagy level in bladder cancer cells, we determined the phosphorylation of ULK1 and its upstream regulators, including AMPK and mTOR." (PMID 32174982, 2020). "The role of autophagy in the regulation of AMPK/mTOR signaling as a response to the CWS-loaded formulations appeared to be insufficient to inhibit cell viability and induce the apoptosis of bladder cancer cells." (PMID 33302414, 2020). "Genome-based subtyping has revealed many oncogenic targets contributing to bladder cancer development, e.g., fibroblast growth factor receptor (FGFR), PI3K (phosphoinositid-3 kinase), Akt (serine/threonine kinase), and mTOR (mechanistic target of rapamycin)." (PMID 32759798, 2020). "Chronic treatment of the bladder cancer cell lines RT112 and UMUC3 with the mTOR-inhibitor temsirolimus triggers resistance characterized by accelerated tumor growth and invasive behaviour." (PMID 31167517, 2019). "The panel of cell lines included in our study possesses diverse molecular alterations in FGFR3, RAS, PIK3CA, PTEN, TSC1 and mTOR that are capable of influencing response to PI3K pathway inhibition and are very frequent in bladder cancer specimen." (PMID 29357370, 2018). "There is the case of a lentiviral sponge for miRNA-21 that has the capacity to reduce glycolysis in bladder cancer T24 cells, via regulation of the PTEN/PI3K/AKT/mTOR axis." (PMID 28703782, 2017). "A recent study revealed that STn antigen expression is related to poorer prognosis in bladder cancer cases, and IHC analysis showed that the expression of STn antigen is related to activated PI3K/AKT/mTOR signaling." (PMID 29348846, 2017). "And, mammalian target of rapamycin (mTOR) gene and insulin-like growth factor 1 receptor (IGF1R) are direct target of miRNA-100 in bladder cancer, acute myelocytic leukemia, endometrioid endometrial carcinoma and so on." (PMID 28977982, 2017).
bladder cancer (continued). "In conclusion, we herein confirm that the fluorinated quercetin derivative, TFQ blocks bladder cancer cells growth and increases apoptotic progression more effective than Que via activating AMPK and blocking the mTOR pathways." (PMID 29069736, 2017). "Metformin inhibits the proliferation of bladder cancer cells in vitro and in vivo through activation of AMPK and mTOR." (PMID 28373897, 2017). "The PPP2R2A/Akt/mTOR axis was required for miR‐222‐induced proliferation and CDDP resistance in bladder cancer cells." (PMID 26800397, 2016). "We found ATR-1 inhibited bladder cancer cell proliferation, arrested cell cycle in G2/M phase, induced apoptosis through the mitochondrial pathway, and blocked the PI3K/Akt/mTOR pathway." (PMID 26931119, 2016). "Together, these data demonstrate that the PPP2R2A/Akt/mTOR axis is required for miR‐222‐mediated proliferation and CDDP‐induced cell death in bladder cancer cells." (PMID 26800397, 2016). "Genetic alterations in the mTOR, FGFR, EGFR, and HER2 pathways have long been recognized in subsets of bladder cancer." (PMID 28105319, 2016). "We have investigated a function for autophagy in a panel of 18 bladder cancer cell lines treated with small-molecule inhibitors targeting nodes of potential therapeutic relevance: FGFR, PI3Kβ/δ, AKT and mTOR (FGFR/PTENi)." (PMID 26853465, 2016). "In conclusion, STn was found to be marker of poor prognosis in bladder cancer and, in combination with PI3K/Akt/mTOR pathway evaluation, holds potential to improve the stratification of stage disease." (PMID 26569621, 2015). "GOLPH3 silencing in bladder cancer cells decrease the cell proliferation, migration and invasion likely by inhibiting AKT/mTOR signaling." (PMID 26375441, 2015). "In conclusion, this study suggests that GOLPH3 is overexpressed in most bladder cancers treated by cystectomy and plays an important role in human bladder cancer progression by modulating AKT/mTOR signaling." (PMID 26375441, 2015). "We report that the PI3K/mTOR dual inhibitor NVP- BEZ235, an orally bioavailable imidazoquinoline derivative synergistically potentiates the antitumor effect of cisplatin in bladder cancer cells." (PMID 24969552, 2014). "In bladder cancer cells, NVP-BEZ235 showed relatively more potent antitumor effect than mTOR inhibitor such as temsirolimus and everolimus." (PMID 24969552, 2014). "In summary, our study demonstrates that metformin effectively inhibits human bladder cancer cell proliferation and tumor growth in vitro and in vivo, possibly by inducing G0/G1 cell cycle arrest and activating AMPK/mTOR pathway." (PMID 24351837, 2013). "However, recent research has proposed different perspectives, suggesting that mTOR inhibition can enhance mitophagy-mediated GPX4 degradation, thereby promoting ferroptosis in bladder cancer cells." (PMID 40305351, 2025). "In this work, it was also found that COP could inhibit the phosphorylation of mTOR in a dose-dependent manner in T24 and BIU-87 cells, suggesting that COP may affect the progression of bladder cancer through modulating autophagy." (PMID 41287122, 2025). "For instance, miR‐100 targets mTOR in bladder cancer, inhibiting cell growth and arresting the G1 phase without inducing apoptosis." (PMID 40754657, 2025). "This led to the hypothesis that activation of the mTOR pathway promotes FADS2 overexpression by enhancing SREBP activity, thereby contributing to the resistance of bladder cancer cells to ferroptosis." (PMID 40682485, 2025). "In addition, the long-term administration of the mTOR inhibitor, everolimus, was shown to induce resistance in RT112, UMUC3, and TCCSUP bladder cancer cell lines." (PMID 38254735, 2024). "Our initial target gene pair, mTOR and STAT3, is highly significant in bladder cancer." (PMID 38886756, 2024). "Molecular pathways like PI3K/AKT/mTOR, activated in obese patients due to high circulating levels of IGF1, could be a potential therapeutic target in bladder cancer patients with high BMI." (PMID 39723162, 2024).
bladder cancer (continued). "Experiments using the UMUC3 bladder cancer cell line revealed that melatonin silences the Notch/JAG2 gene and represses the PI3K/AKT/mTOR signaling, suggesting a link between both signaling pathways responsible for proliferation, invasion and metastasis in this type of cancer." (PMID 38473317, 2024). "Here we found that MB-10 also inhibited mTOR and activated autophagy in priBlCa-1 cells, yet autophagy inhibitors failed to mitigate MB-10-induced cytotoxicity in bladder cancer cells." (PMID 38467612, 2024). "Ubiquitin C-terminal hydrolase-L5 (UCHL5), a member of the DUBs family of proteins that is overexpressed in bladder cancer, has been indicated to promote the growth and migration of bladder cancer cells by increasing MYC expression through the AKT/mTOR signaling pathway." (PMID 39031286, 2024). "FIN56 could promote autophagy-mediated GPX4 degradation and induce the ferroptosis of bladder cancer cells, and FIN56 and the mTOR inhibitor Torin 2 synergistically killed bladder cancer cells." (PMID 38247539, 2024). "Subsequently, we examined whether the mTOR and STAT3 double knockdown would prove more advantageous than single gene knockdowns of each gene as a therapeutic strategy in bladder cancer." (PMID 38886756, 2024). "Kawain selectively inhibits the growth of bladder cancer cell lines over non-malignant urothelial cells and downregulates mTOR signaling." (PMID 36838656, 2023). "IGF2 regulates PI3K/AKT/mTOR signaling pathway, targeting on IGF2 is a new therapeutic strategy for bladder cancer, and obstructing IGF2 signaling way could make cancer cell reacquire sensitivity to Taxol." (PMID 36512456, 2023). "In addition, bladder cancer cells and transplanted tumors with OTUD5 knockdown are more sensitive to the mTOR inhibitor everolimus, which provides new ideas for personalized treatment of bladder cancer patients in the future." (PMID 36085200, 2022). "FXR overexpression reduced the cholesterol contents in human TSGH8301 and T24 bladder cancer cells, and this effect may depend on the inhibition of the PI3K/AKT/mTOR signaling pathway." (PMID 36139556, 2022). "While significant work has gone into analysis of molecular alterations of the mTOR pathway in bladder cancer, this has not yielded significant benefit in mTOR-targeted therapy approaches in urothelial carcinoma to date." (PMID 35326708, 2022). "CDCA5 was overexpressed in bladder cancer tissues and activated PI3K/AKT/mTOR pathway." (PMID 35509067, 2022). "Furthermore, NFKBIZ has been shown to be downregulated in bladder cancer and to affect the PI3K/AKT/mTOR pathway to inhibit proliferation." (PMID 35499706, 2022). "NVP-BEZ235 (Dactolisib) is an oral mTOR/PI3K dual inhibitor and has been shown to suppress tumor cell growth by inducing cell cycle arrest and caspase-dependent apoptosis in eight different human bladder cancer cell lines." (PMID 35326708, 2022). "Since OMWW blocks the cell cycle through the manipulation of the cyclin-CDK axis and the deactivation of Akt-mTOR signaling, OMWW could become relevant in supporting bladder cancer therapy." (PMID 35057550, 2022). "These outcomes suggest that FXR might reduce cholesterol biosynthesis by inhibiting the PI3K/AKT/mTOR signaling pathway and subsequently decreasing the expression of SREBP2 and HMGCR in human TSGH8301 and T24 bladder cancer cells." (PMID 36139556, 2022). "Puerarin also inhibits bladder cancer cell viability through cell cycle arrest at the G0/G1 phase by a mechanism that involves downregulation of mTOR and p70S6K phosphorylation, without affecting their protein levels." (PMID 33996570, 2021). "Previously, we noted that in bladder cancer, SPAG5 is involved the AKT/mTOR pathway." (PMID 34162370, 2021).
bladder cancer (continued). "Pre-clinical work in bladder cancer and extensive studies in other cancers suggest that MEK inhibition could be a potential combination approach to PI3K/AKT/mTOR inhibition, by targeting a parallel compensatory pathway." (PMID 33216841, 2020). "Therefore, the present study was designed to investigate metastatic characteristics of bladder carcinoma under short- and long-term SFN treatment, combined with the mTOR-inhibitor, everolimus." (PMID 32759798, 2020). "Recently, we reported that an mTOR inhibitor induced the initiation of autophagy, but it was not adequate to enhance cell death, owing to the protective effect of NBR1, an antioxidant-related gene, in bladder cancer cells." (PMID 33302414, 2020). "Nevertheless, although mTOR-inhibition has been shown to be useful in treating bladder cancer, the benefit is not as strong as expected." (PMID 31167517, 2019). "Our results indicate that bladder cancer cells are sensitive to dual PI3K/mTOR inhibitors regardless of their genetic background." (PMID 29357370, 2018). "In conclusion, this study demonstrated that flaccidoxide-13-acetate inhibits the migration and invasion of T24 and RT4 bladder cancer cells through the down-regulation of MMP-2 and MMP-9 expressions, and the process is controlled by the FAK/PI3K/AKT/mTOR pathway." (PMID 29280977, 2017). "Results of Moon and colleagues suggested that the possible crosstalk between Akt/mTOR and MAPK/ERK pathway might help NVP-EBZ235 and cisplatin combination therapy treat bladder cancer." (PMID 28746469, 2017). "We used immunostaining to examine whether flaccidoxide-13-acetate affects bladder cancer cell invasion and metastasis via the FAK/PI3K/AKT/mTOR signaling pathway." (PMID 29280977, 2017). "In the present study, we found that miR‐222 promoted the proliferation of bladder cancer cells and attenuated CDDP‐induced cell death by regulating the PPP2R2A/Akt/mTOR axis, which indicated that miR‐222 might be a novel therapeutic target for bladder cancer." (PMID 26800397, 2016). "Given that several mTOR inhibitors and S6K1 inhibitors have been tested as adjuvants of chemotherapy, further study of the potential application of evodiamine and TRAIL combination in bladder cancer therapy is warranted." (PMID 24566141, 2014). "Although we have identified a role for mTORC1 in promoting bladder cancer proliferation in vitro and bladder cancer xenograft growth in vivo, the role of mTOR signaling in bladder cancer invasion has not been explored." (PMID 24312263, 2013). "We recently demonstrated that a panel of nine bladder cancer cell lines exhibits relative differences in their RAD001 sensitivity and accordingly, RAD001 treatment resulted in relative differences in mTOR inhibition and growth arrest, as monitored by MTT assays." (PMID 23799002, 2013). "Clonogenic assays were performed using 6 bladder cancer cell lines (UM-UC3, UM-UC5, UM-UC6, KU7, 253J-BV, and 253-JP) in order to examine the effects of ionizing radiation (IR) alone and in combination with RAD001, an mTOR inhibitor." (PMID 23799002, 2013). "Thus, it is hypothesised that mTOR activation upregulates SREBP activity, which in turn promotes FADS2 overexpression, contributing to ferroptosis resistance in bladder cancer cells and facilitating cancer progression." (PMID 40682485, 2025). "In addition to the mTOR signaling pathway, we found that MIR4435-2HG could mediate the transcriptional activation of cell cycle signaling in bladder cancer, which may affect epigenetic modulation." (PMID 37355516, 2023). "We have previously demonstrated that SHR-5 and one of its bioactive components, salidroside, inhibit the growth of bladder cancer cell lines with minimal effect on the growth of non-malignant bladder urothelial cells via the inhibition of the mTOR pathway and induction of autophagy." (PMID 37370698, 2023).